IL1R2 (interleukin 1 receptor type 2)
Diseases named in the same sentence as IL1R2 in open-access papers (continued):
Sharing a sentence is not in itself a finding about the gene and the disease.
COVID-19 (22 papers, 2020 to 2025). A disease caused by infection with severe acute respiratory syndrome coronavirus 2. "Dexamethasone treatment of COVID-19 patients was associated with the upregulation of IL-1R2 in immunosuppressive neutrophils." (PMID 41087719, 2025). "Of the DEGs that overlapped between healthy and COVID-19 PBMCs, 17 were upregulated, among which IL1R2, whereas the genes encoding for the cytokine tumor necrosis factor superfamily member 15 (TNFSF15) and ACOD1 were downregulated by dexamethasone." (PMID 37614228, 2023). "Dexamethasone during severe COVID-19 affected circulating neutrophils, altered IFNactive neutrophils, downregulated interferon-stimulated genes and activated IL-1R2+ neutrophils." (PMID 34782790, 2022). "The levels of intracellular TNFα and interleukin 1 receptor type 2 (cIL1R2) in leukocytes were higher in HCs than in COVID-19 patients during their first ICU week (p < 0.001)." (PMID 35625671, 2022). "In our non-randomized, pragmatic investigation, dexamethasone in severe COVID-19 affected circulating neutrophils, altered the IFNactive state, downregulated interferon-responsive genes and activated IL-1R2+ neutrophils." (PMID 34782790, 2022). "According to our findings, IL1R2 is a downregulated NP marker for COVID-19 patients." (PMID 35922752, 2022). "Interestingly, scRNA-seq unveiled a cluster of immature CD14+ monocytes, with low HLA-DR and expressing MPO, PLAC8, and IL1R2, in the blood of COVID-19 patients and similar cells were reported in sepsis." (PMID 33674591, 2021). "Moreover, the roles of anti-inflammatory cytokines in COVID-19 pathogenesis, including IL1R2, IL1RN, IL10, and TGFB1, are unclear and should be investigated in the future." (PMID 33101705, 2020). "In addition, neutrophil-cluster 6 showed particularly low and high expression of Il1r2 and Isg20, respectively, thereby recapitulating the phenotypes seen for immunosuppressive and IFNactive neutrophils in the peripheral blood of COVID-19 patients." (PMID 35339689, 2022). "Further analysis of gene importance across the four models revealed that the top four hub genes in COVID-19 were CR1, TNFRSF10C, TAP2, and TGFBI, while the top four hub genes in SS-KCS were CR1, IL13, TAP2, and IL1R2." (PMID 40149556, 2025). "The genes that are up-regulated in COVID19-ACEi, IL1R2 and RETN were clustered with markers of COVID-19 immunopathology, SPO2, and 3 other down-regulated genes." (PMID 36817759, 2022). "Intriguingly, we noticed relatively higher expression levels of anti-inflammatory (IL1R2) and immune suppressive (RETN) genes in MDSC monocytes of hospitalized COVID-19 patients with the use of ACEis; consistent with the immunosuppression function of MDSCs." (PMID 36817759, 2022). "In regard to cytokines and chemokine expression between COVID-19 cases we found that the highest avg (log2) values showing fold change were indicated by CCL5, IL1R2, NAMPT and PPBP." (PMID 34824360, 2021). "The increased expression of IL-1 inhibitory receptor 2 (IL1R2) in MDSC monocytes is interesting considering the role of dysregulated monocyte responses and elevated levels of serum inflammatory cytokine, including IL-1β reported in severe COVID-19 patients." (PMID 36817759, 2022). "For example, increased expressions of IL10, IL1R2 mRNA and decreased expression of CD74 and CIITA mRNA were described in monocytes of progressive COVID-19 patients compared with stable patients suggesting the acquisition of a regulatory phenotype by myeloid cells." (PMID 36389738, 2022). "IL1R2, known as anti-inflammatory cytokines, is highly expressed in monocyte-macrophages from BALF and follicular regulatory T (TFR) cells; however, TFR cells have been reported to be significantly lower in hospitalized COVID-19 patients." (PMID 35922752, 2022).
COVID-19 (continued). "Regarding neutrophils, the increased expressions of CD177, IL1R2 and S100A9 in our study agree with the existing literature, which points towards the induction of a dysregulated neutrophil function in COVID-19 patients with increased NET production that aggravates the pathophysiology of COVID-19." (PMID 36389738, 2022). "RSAD2 and IL1R2 were also found to be involved in regulation of SARS-CoV-2 infection, however their expression were positively correlated only with viral load and viral shedding time, whereas their association with COVID-19 severity has not yet been shown." (PMID 34807957, 2021).
breast carcinoma (13 papers, 2020 to 2025). "IL-1β can promote the release of the intracellular domain of IL-1R2 (icd-IL-1R2), and the increased IL-1R2 in breast cancer can promote the self-renewal and proliferation of breast tumor cells." (PMID 40767963, 2025). "Consistently, IL1R2 enhances breast cancer cell proliferation in vitro, and facilitates xenograft tumor growth in vivo." (PMID 34575114, 2021). "IL1R2, a negative immune regulator, serves as a diagnostic marker for acute myocardial infarction and is implicated in promoting breast cancer cell proliferation and invasion." (PMID 39655195, 2024). "Furthermore, it has been reported that IL1R2 is upregulated in breast cancer, and higher expression is correlated with lower survival rates in humans." (PMID 39911484, 2024). "Moreover, the characterization of IL-1R2 expression in all breast cancer subtypes by immunohistochemistry on a tumor tissue array highlighted the elevated IL-1R2 levels in tumors compared to normal tissue." (PMID 33924428, 2021). "Moreover, the analysis of the TCGA cohort reported that breast cancer patients harboring a high IL1R2 mRNA expression in tumors have a poorer overall survival and relapse-free survival (RFS)." (PMID 33924428, 2021). "Therefore, IL1R2 was reported to be a potential therapeutic target for breast cancer treatment." (PMID 35388653, 2022). "Furthermore, IL1β treatment could induce icd‐IL1R2 release in a time‐ and dose‐dependent manner in IL1R2‐overexpressing breast cancer cells, and IL1R2 neutralizing antibody pretreatment reversed IL1β induced BMI1 upregulation in breast cancer cells." (PMID 31921558, 2020). "The in vitro and in vivo study suggested that overexpression of IL1R2 leads to down-regulation of USP15, and helps in controlling breast cancer malignancy." (PMID 35388653, 2022). "IL1R2 binds and increases the activity of the ubiquitin-specific protease 15 (USP15) in breast cancer cells." (PMID 35388653, 2022). "Elevated expression of Interleukin-1 receptor type 2 (IL1R2) is demonstrated in the BTIC population, and is relevant to poor prognosis in breast cancers." (PMID 34575114, 2021). "The analysis of RNA-seq or scRNA-seq datasets from studies comparing T-cell-infiltrating tumor tissue with those from NAT and blood in breast carcinoma, CRC and NSCLC highlighted an increased IL1R2 gene expression on TA-Tregs." (PMID 33924428, 2021). "Here, it is found that a negative immune regulator interleukin‐1 receptor type 2 (IL1R2) is upregulated in breast cancer (BC) tissues and especially in BTICs." (PMID 31921558, 2020).
Arthritis (12 papers, 2015 to 2025). Inflammation of a joint. "Many studies reported that the IL1R2 as a protected factor can decrease the risk of many diseases, such as IgA nephropathy, Arthritis, and atherosclerosis." (PMID 30672138, 2019). "To further assess the severity of arthritis, we measured the mRNA levels of a variety of pro-inflammatory cytokines and chemokines, including Il18bp, Il18, Il1b, Il6, Il1r2, Ifng, Cxcl9, Cxcl1, and Cxcl2 in arthritic joints of IL-18BP KO and WT littermates." (PMID 37415987, 2023). "In animal models of arthritis, IL-1-induced inflammation andcardiac allograft surgery, overexpression of IL-1R2 hasanti-inflammatory profiles." (PMID 39076182, 2022). "Overexpression of IL-1R2 had protective effects in rabbit arthritis or mouse heart transplantation models." (PMID 36140754, 2022). "The relevance of IL-1R2 in tuning inflammation was further highlighted in the K/BxN serum transfer arthritis model." (PMID 35211118, 2022). "In in vitro and in vivo experiments, expression of IL1R2 has been identified as an anti-inflammatory mediator with therapeutic value in several diseases including arteriosclerosis and arthritis." (PMID 32727543, 2020). "IL-1R2 inhibits collagen-induced arthritis by downregulation of the IL-1 signaling cascade in macrophages." (PMID 30042333, 2018). "IL1-r2 suppresses the immune response to IL-1 reducing arthritis in mice." (PMID 40861855, 2025). "IL-1R2 was shown to play important roles in several diseases such as diabetes, atherosclerosis, sepsis, Alzheimer’s disease, autoimmune inner ear disease (AIED), ulcerative colitis, and arthritis." (PMID 30042333, 2018).
atherosclerosis (9 papers, 2014 to 2025). A disease characterized by the build-up of fatty material and calcium deposition in the arterial wall resulting in partial or complete occlusion of the arterial lumen. "IL-1-mediated inflammation contributes to the pathology of many diseases including systolic heart failure, and IL-1R2 has been implicated in atherosclerosis." (PMID 33195475, 2020). "During atherosclerosis and vascular injury, the expression level of IL1R2 on monocytes/macrophages is downregulated." (PMID 40933471, 2025). "Increased interaction of various ligand-receptor pairs including Ccl2-Ccr2, Ccl7-Ccr2, and Il1b-Il1r2 between Mesen II and inflammatory cells in ApoE−/− adventitia further implied the participation of Mesen II in early development of atherosclerosis." (PMID 30943771, 2019). "For example, IL18R1 was enriched in the TNF signaling pathway and cytokine–cytokine receptor interaction; PFKFB3 was enriched in fructose and mannose metabolism and HIF-1 signaling pathway; IL1R2 was enriched in hematopoietic cell lineage and fluid shear stress and atherosclerosis." (PMID 34336943, 2021). "Many of the genes differentially regulated during monocyte-to-macrophage differentiation (downregulated genes include JAK2, STAT6, TLR8, and TLR2, and upregulated genes include VEGFB, TGFB1, FN1, IL-1R2, SCARB1, MSR1, and CD163) have been previously reported in the pathogenesis of atherosclerosis." (PMID 25011540, 2014).
ulcerative colitis (9 papers, 2018 to 2025). An inflammatory bowel disease involving the mucosal surface of the large intestine and rectum. "The activity of IL-1R2, linked to ulcerative colitis, is influenced by the BACE2 gene." (PMID 38962743, 2024). "IL-1R2 has also been studied in the ulcerative colitis model using DSS; the degree of inflammation in mice with IL-1R2 deficiency is reduced, suggesting that IL-1R2 plays a pro-inflammatory role in this model." (PMID 40767963, 2025). "Previous studies in ulcerative colitis have demonstrated that blocking IL-1R2 upregulated the expression of pro-inflammatory chemokines induced by Il-1β, such as TNF-a, IL-6 and IFN-γ." (PMID 35087030, 2022). "IL1R2 expressed by epithelial cells acts as a homeostatic regulator in the remission of ulcerative colitis." (PMID 35559024, 2022). "A recent study by Mora-Buch and coworkers showed that IL-1R2 production by epithelial cells was increased during remission of ulcerative colitis." (PMID 30042333, 2018). "In addition, individuals with ulcerative colitis (UC) or Crohn’s disease had lower serum levels of IL-1R2." (PMID 38329807, 2024). "Finally, transcriptional and protein analysis showed that IL-1R2 was a favorable prognostic marker in ulcerative colitis, being up-regulated in intestinal mucosal cells from ulcerative colitis patients in remission phase." (PMID 35211118, 2022). "Finally, patients with ulcerative colitis or Crohn’s disease had lower serum IL-1R2." (PMID 38329807, 2024). "IL1R2 is a decoy receptor that IL1A can bind in order to prevent IL1A mediated signal transduction and may play protective roles in chronic inflammatory diseases like ulcerative colitis and liver cirrhosis." (PMID 33995488, 2021).
acute myocardial infarction (8 papers, 2022 to 2025). Necrosis of the myocardium, as a result of interruption of the blood supply to the area. "Furthermore, IL1R2 is a diagnostic marker for acute myocardial infarction (AMI) and post-traumatic stress disorder (PTSD)." (PMID 38271077, 2024). "Here we found that the serum levels of IL-1R2 were significantly increased in patients with acute myocardial infarction (AMI) following interventional therapy." (PMID 35087030, 2022). "The role of soluble interleukin-1 receptor type 2 (sIL-1R2)in acute myocardial infarction (AMI) remains undocumented." (PMID 39076182, 2022). "Moreover, the rate of Il1r2 was also higher on the third day after myocardial infarction than the first day, which revealed the potential of Il1r2 in predicting the progression of MI." (PMID 40231027, 2025). "In the study, IL1R2 has been shown to inhibit cardiomyocyte apoptosis during myocardial ischemia-reperfusion injury, suggesting its potential as a therapeutic target for the prevention and treatment of myocardial infarction." (PMID 40231027, 2025). "Meanwhile, a study comfirmed that in acute myocardial infarction (AMI), the expression of IL1R2 in M2 type macrophages was elevated, which was a potential biomarker of AMI67." (PMID 37041166, 2023).
prostate carcinoma (8 papers, 2011 to 2023). A carcinoma that arises from epithelial cells of the prostate gland. "Our findings revealed a modest increase in prostate cancer risk for unadjusted and adjusted logistic regression models for IL1R2 rs11886877 among men of African Descent." (PMID 24359571, 2013). "Among U.S. men, age-adjusted dominant, recessive and additive genetic models for the IL1R2 rs11886877 locus were linked to an increase in prostate cancer susceptibility." (PMID 24359571, 2013). "Although this study displays a modest association between inflammatory-related cytokine variant IL1R2 rs11886877 and prostate cancer risk, this relationship has yet to be tested biologically." (PMID 24359571, 2013). "The association of IL1R2 rs11886877 with prostate cancer risk may prove to be strong in a larger study population." (PMID 24359571, 2013). "Elevated IL-1R2 expression has been observed in various cancers, such as pancreatic ductal adenocarcinoma, prostate cancer, and benign prostatic hyperplasia." (PMID 38089928, 2023). "Similar to the total population, inheritance of sequence variants in IL1R2, IL10RA and TNF among U.S. men were linked with a significant increase in prostate cancer risk." (PMID 24359571, 2013). "Among U.S. men, two inflammatory-related sequence variants, [IL1R2 rs11886877 (GA, GA + AA, AA) and IL10RA rs4252243 AA], were associated with a 1.82-2.49-fold increase in prostate cancer risk." (PMID 24359571, 2013). "TMPRSS2/ERG fusion gene indirectly up-regulates ZEB2, a facilitator of the epithelial to mesenchymal transition (EMT), by binding to IL1R2 to increase prostate cancer tumorigenesis." (PMID 24359571, 2013). "In the total population, inheritance of the IL1R2 rs11886877 AA, IL8RB rs11574752 AA, TNF rs1800629 GA + AA, and TNF rs673 GA genotypes modestly increased prostate cancer risk by 1.45 to 11.7-fold relative to the referent genotype." (PMID 24359571, 2013). "Notably, several studies have demonstrated IL‐1R2 abnormal expression in various cancers, such as lung cancer, prostate cancer, and adrenocortical cancer." (PMID 30895747, 2019). "Upon stratification by study center, the IL1R2 rs11886877 locus was marginally related to prostate cancer among men of African descent from the U.S. However, overall the inflammatory-related sequence variants were not robustly related to prostate cancer among our study participants." (PMID 24359571, 2013). "In acute myeloid leukemia (AML), IL1R2 gene expression was associated with bad prognosis, in ovarian cancer, IL1R2 was upregulated in recurrent compared to primary cancer and in prostate the molecule was expressed in prostatic cancer cells but not in normal cells." (PMID 35211118, 2022). "Despite this, we cannot eliminate the possibility that IL1R2 and other inflammatory-related sequence variants not included in this study may influence the risk of prostate cancer development or aggressive tumor behavior." (PMID 24359571, 2013). "Leshem and colleagues (2011) found that the promoter region of IL1R2 possesses putative binding motifs for the TMPRSS2/ERG fusion gene, which is highly expressed in aggressive prostate cancer." (PMID 24359571, 2013). "Currently, there are no published reports on the relationship between IL1R2 rs11886877 and prostate cancer for any population." (PMID 24359571, 2013).
asthma (7 papers, 2015 to 2024). "In the present study, we measured DNA methylation at the IL1R1 and IL1R2 gene loci and assessed for associations with asthma-related phenotypes and gene expressions." (PMID 26246860, 2015). "In this study, we hypothesized that DNA-Me in the promoters of IL1R1 and IL1R2 is associated with asthma and/or atopy." (PMID 26246860, 2015). "Together, they underline the relevance of IL1R2 as a potential biomarker of asthma and atopy." (PMID 26246860, 2015). "IL-36, IL-38, and IL-3 are believed to be new members of the IL-1 family and are involved in the pathogenesis of asthma, and hypermethylation of IL1R2 (2q11.2) in blood shows asthma-related phenotypes." (PMID 34566492, 2021). "We reported the association of polymorphisms within the IL1 receptors type I (IL1R1) and type II (IL1R2) gene loci with asthma and atopy in the French Canadian Saguenay–Lac-Saint-Jean (SLSJ) asthma study." (PMID 26246860, 2015). "IL1R2 has increased expression in adults with allergic asthma compared to those with nonallergic asthma and is positively associated with severity." (PMID 36864187, 2023). "Additionally, I can confirm that IL1 family members of IL1R2 have a high significance in severe and moderate-to-severe asthma gene sets, in which p-values are > 4.4 (−log10)." (PMID 32512817, 2020). "We identified potential binding sites for transcription factors relevant to asthma near the CpG dinucleotide sites of IL1R2 analyzed which could explain the inverse correlation between methylation and gene expression." (PMID 26246860, 2015). "Atopic and non-atopic asthma were associated with DNA-Me at IL1R2 but not atopy alone (data not shown)." (PMID 26246860, 2015). "In this study, we detected higher levels of DNA-Me at IL1R2 among affected individuals (i.e., with asthma, atopy, or both) as compared to non-affected controls (Δβ = 8.02 %, p value = 0.013, and Δβ = 3.72 %, p value = 0.012 for IL1R2-CpG2 and the mean for CpG3 and CpG4, respectively)." (PMID 26246860, 2015). "This hypothesis could be attributed to both asthma and atopy as IL1R2 non-signaling receptor is suspected to influence Th2 imbalance, and both disorders are driven by Th2 allergic lung inflammation." (PMID 26246860, 2015). "According to these analyses, IL-1R2, BAX, and TGFB1 were of particular interest due their “High” relationship level with allergic asthma and “Moderate” or weaker relationship value with allergy or nonallergic asthma." (PMID 33936056, 2021).
ovarian carcinoma (6 papers, 2008 to 2025). A malignant neoplasm originating from the surface ovarian epithelium. "Notably, the inclusion of inflammatory mediators, such as IL1R2, reflects the critical role of inflammation in ovarian cancer pathogenesis, particularly in the context of tumor–platelet interactions." (PMID 40227838, 2025). "IL1R2 may provide an insight into the biology of recurrent ovarian tumors, suggesting an initial immune response to the relapsing neoplasm and may secondly represent a surrogate marker of recurrence in ovarian cancer." (PMID 18211683, 2008). "The top distinctive genes for the proliferation metaprofile include, besides previously used markers, numerous genes related to malignancy and ovarian cancer progression, in particular cytokines and their receptors: CXCL1, IL1A, CXCL8, IL1B, IL1R1, and IL1R2." (PMID 29362714, 2017).